MACROD2 (mono-ADP ribosylhydrolase 2)
Diseases named in the same sentence as MACROD2 in open-access papers (continued):
Sharing a sentence is not in itself a finding about the gene and the disease.
Kabuki syndrome (3 papers, 2018 to 2022). Kabuki syndrome (KS) is a multiple congenital anomaly syndrome characterized by typical facial features, skeletal anomalies, mild to moderate intellectual disability and postnatal growth deficiency. "It is worth mentioning that the association between an intron deletion of MACROD2 gene and kabuki syndrome is reported in a small number of clinical cases." (PMID 30991935, 2019). "A mutation screening revealed a 250 kilobase de novo microdeletion at 20p12.1, which hits intron 5 of MACROD2 gene and associates in one patient with kabuki syndrome." (PMID 30991935, 2019). "Disruption in the gene encoding for MACROD2, a mono-ADP-ribosylhydrolase, has been associated to the Kabuki syndrome, a pediatric congenital disorder characterized by facial anomalies, and mental retardation." (PMID 30619475, 2018). "Exon 5 of MACROD2 gene was originally found disrupted in Japanese children affected by the Kabuki syndrome, a rare, clinically congenital mental retardation syndrome of unknown etiology, characterized by facial anomalies and mental retardation." (PMID 30619475, 2018).
epilepsy (2 papers, 2015 to 2018). A brain disorder characterized by episodes of abnormally increased neuronal discharge resulting in transient episodes of sensory or motor neurological dysfunction, or psychic dysfunction. "These microdeletions affected 158 protein-coding RefSeq genes and exhibited an enrichment of genes previously associated with epilepsy (NRXN1, RBFOX1, PCDH7, KCNA2, EPM2A, RORB, PLCB1) and neuropsychiatric disorders (DPYD, CADM2, PARK2, GRM8, TSNARE1, TPH2, MACROD2)." (PMID 25950944, 2015).
hepatocellular carcinoma (2 papers, 2020 to 2022). A malignant tumor that arises from hepatocytes. "Similarly, a loss of Macrod2 inhibited GSK-3β activity and activated β-catenin signaling in hepatocellular carcinoma." (PMID 36010655, 2022).
intestinal tumor (2 papers, 2019 to 2020). "Given that the status of MACROD2 is significantly relevant to the intestinal tumorigenesis and plays a crucial role in cancer development, our classifiers are expected to be prognostic indicators for evaluating the malignancy of intestinal tumor." (PMID 31921812, 2019).
liver cancer (2 papers, 2021 to 2022). An epithelial or non-epithelial malignant neoplasm that arises from the liver. "The genes MACROD2 in pancreatic cancer and CDKN2B in liver cancer also show significant differential expression between samples with SVs at these loci relative to those without SVs." (PMID 36163358, 2022).
major depression (2 papers, 2021 to 2022). "Two other patients (Case 5 with CNTN4 deletion and Case 6 with MACROD2 deletion) had a comorbidity of major depressive disorder." (PMID 35611833, 2022).
Anxiety (1 paper, 2021). Intense feelings of nervousness, tension, or panic often arise in response to interpersonal stresses. "Interestingly, Macrod2 KO hyperactivity was not correlated with a decrease in anxiety (less anxiety might mean more activity) as determined by LMA open field and bright field." (PMID 33578760, 2021).
diabetes (1 paper, 2023). "Furthermore, genetic variants within the MACROD2 gene have been positively associated with VAP-1 levels in adipose tissue, a key protein during adipogenesis, and serum levels of VAP-1 can predict mortality in patients with diabetes after 10 years of follow up." (PMID 37049393, 2023).
emphysema (1 paper, 2021). "Comparing with DEGs identified in a preceding emphysema RNA-seq analysis, MACROD2 upregulation in emphysema overlapped with a region identified in the GWAS in all subjects." (PMID 34404834, 2021). "In addition, we identified SNPs at a suggestive level of significance near MACROD2 which is DEG identified in preceding emphysema RNA-seq analysis." (PMID 34404834, 2021). "MACROD2 was associated with COPD and lung function in previous studies, but there is lack of data on the association with emphysema directly." (PMID 34404834, 2021).
esophageal carcinoma (1 paper, 2020). A primary or metastatic malignant neoplasm involving the esophagus. "p < 10-2), loss of MACROD2 in esophageal carcinoma (ESCA) (adj." (PMID 32635458, 2020).
Gilbert syndrome (1 paper, 2021). An autosomal recessive inherited disorder characterized by unconjugated hyperbilirubinemia, resulting in harmless intermittent jaundice. "Array-CGH showed two intronic deletions involving MACROD2 and COMMD10 genes, which could be related to a congenital heart defect; whole exome sequencing highlighted the genotype compatible with Gilbert syndrome." (PMID 34829491, 2021).
Hypercholesterolemia (1 paper, 2020). An increased concentration of cholesterol in the blood. "In addition, mutations of MACROD2 may cause hypercholesterolemia." (PMID 33352859, 2020).
intestinal cancer (1 paper, 2019). "The candidate SNP sites identified by our prediction model can be applied as biomarkers for the pathologic evaluation of CRC, given that the state of MACROD2 has been confirmed to be a significant signal in intestinal cancers." (PMID 31921812, 2019).
kidney tumors (1 paper, 2022). "Only one somatic SNV associated with kidney tumors has been reported in the ERV1 MACROD2 region." (PMID 36575684, 2022).
leukaemia (1 paper, 2020). "For MACROD1, a RUNX-MACROD1 fusion was identified in leukaemia and, for MACROD2, a PDGFRA-MACROD2 fusion in a pleomorphic sarcoma." (PMID 32151005, 2020).
liver disease (1 paper, 2024). "A subsequent genome-wide association study (GWAS) identified shared single-nucleotide polymorphisms (SNPs) in the genes AR, EDIL3, MACROD2, PCSK5, RUNX1T1, TENM4, and ZEB2 between PN and liver disease from the FinnGen cohort." (PMID 38397136, 2024).
neuroblastoma (1 paper, 2020). Neuroblastoma (NB) is the most common solid, extracranial childhood tumor. "MACROD1 is most prevalent in mitochondria of skeletal muscle, MACROD2 localises to nucleo- and cytoplasm and is found so far only in neuroblastoma cells, whereas the more ubiquitously expressed TARG1 is present in nucleoplasm, nucleolus and stress granules." (PMID 32427867, 2020).
Parkinson disease (1 paper, 2021). A progressive degenerative disorder of the central nervous system characterized by loss of dopamine producing neurons in the substantia nigra and the presence of Lewy bodies in the substantia nigra and locus coeruleus. "Most interestingly, the Macrod2 KO hyperactivity phenotype was conversely paired with a bradykinesia type gait (slower, shorter steps as appears in Parkinson’s disease)." (PMID 33578760, 2021).
psoriasis (1 paper, 2021). An autoimmune condition characterized by red, well-delineated plaques with silvery scales that are usually on the extensor surfaces and scalp. "Although no alteration in the expression profile of the gene encoding PARG was found, the transcript levels of the genes encoding several PAR hydrolases, namely MACROD1, MACROD2, and TARG1 were lower in psoriasis lesional skin." (PMID 34748530, 2021).
psychosis (1 paper, 2018). "In summary, the three newly identified genes (MACROD2, RAC1, and SPHK1) are related to brain functions and have plausibility for involvement in the pathophysiology of psychosis." (PMID 29695761, 2018).
squamous carcinoma (1 paper, 2021). "It was found that in 2,616 coding genes, 2 or more integration sites presented among samples, like RAD51B, MACROD2, FHIT, CSMD1, LRP1B, and DLG2, which had already been previously reported as frequent sites of integration in squamous carcinoma samples." (PMID 33810183, 2021).
cancer (21 papers, 2013 to 2024). A tumor composed of atypical neoplastic, often pleomorphic cells that invade other tissues. "Abnormalities in the sequence of the gene locus of MACROD2, most often deletions or single nucleotide polymorphisms (SNPs), have been consistently associated with cancers, neurological and psychiatric disorders." (PMID 30619475, 2018). "At the time of submission of this manuscript, we have interrogated the Catalogue Of Somatic Mutations In Cancer (COSMIC) and retrieved 94 SNPs hitting MACROD2 in various cancers." (PMID 30619475, 2018). "Detailed studies are required to determine how loss of MACROD2 might cooperate with loss of APC to drive cancer." (PMID 32151005, 2020). "Importantly, some MACROD2 somatic mutations observed in cancer are predicted to interfere with binding of ADP-ribose to the catalytic pocket of MacroD2, therefore leading to increased sensitivity to genotoxic stress, and chromosomal instability in CRC." (PMID 30991935, 2019). "In addition, MACROD2 deletion in CRC is significantly associated with the extent of malignancy, indicating that MACROD2 acts as a haploin-sufficient tumor suppressor, with the loss of function promoting chromosome instability and thereby driving cancer evolution." (PMID 31921812, 2019). "Eight SVs were detected in the MACROD2 gene region in two samples, which is known as a fragile site in cancer." (PMID 33910608, 2021). "More studies are urgently needed to clarify the exact role of MACROD2 in both the onset of cancer as well as in the response of existing tumours to therapies." (PMID 32151005, 2020). "MACROD1, MACROD2, and OARD1 (TARG1) exhibit mutations only in 0.9%, 2.6%, and 1% of cancer patient samples, respectively, from over 1000 samples in the cBioPortal curated dataset." (PMID 32151005, 2020). "Especially, several top-ranked features showed strong biological and biomedical relevance with MACROD2, indicating that they also play relevant functions in cancer progression." (PMID 31921812, 2019). "One balanced rearrangement studied in detail was shown to result in the fusion of two genes known to be involved in cancer (MACROD2 and ROR1)." (PMID 28655341, 2017). "Several genomic regions containing fragile sites, such as the FHIT gene locus at 3p14.2, RBFOX1 at 16p13.3 and MACROD2 at 20p12.1 that were targeted for deletion in MSS cancers, were also relatively commonly deleted in BRAFmut/MSI cancers." (PMID 24651849, 2014). "Using IHC with a custom antibody, varying levels of MACROD2 were detected in primary and secondary tumour tissues of these patients, collectively showing that MACROD2 may be overexpressed in cancer tissues." (PMID 32151005, 2020). "We previously reported that the MACROD2 locus at chromosome 20p12.1 may be a cancer-specific fragile site often affected in PDAC." (PMID 28927421, 2017). "A number of analyses suggest MACROD2 may play a potential role in cancer." (PMID 32151005, 2020). "In this review, we critically assess the available literature on a role for the hydrolases in cancer and find that, currently, there is limited evidence for a role for MACROD1, MACROD2, or TARG1 in tumorigenesis." (PMID 32151005, 2020). "Such rules and features described specific CNV characteristics contributing to the identification of MACROD2 status and CRC classification, indicating their crucial roles in cancer development." (PMID 31921812, 2019). "The BRAFmut/MSI cancers had substantially fewer MCRs than the MSS cohorts, however they did have a comparatively high proportion of cancers (≥20%) with focal deletions at 3p14.2 (FHIT), 16p13.3 (RBFOX1) and 20p12.1 (MACROD2)." (PMID 24651849, 2014). "Based on DNA copy number analysis of over one-thousand human cancers representing ten different tumor types, we observed five loci with focal deletion frequencies above 5%, including the A2BP1 gene at 16p13.3 and the MACROD2 gene at 20p12.1." (PMID 23805207, 2013).
cancer (continued). "Six of these genes (FHIT, TMSL3, PARK2, A2BP1, MACROD2 and MAP2K4) have been consistently reported as deleted in CRC and other cancers." (PMID 24367615, 2013). "Notably, genes within common fragile sites, such as PRKN and MACROD2, which are among the top 10 scoring genes, showed an exorbitant impact in metastasized CRC, highlighting their potential relevance in cancer." (PMID 39230704, 2024). "Despite the presence of several publications reporting a correlation between MACROD1 or MACROD2 levels and cancer development or progression, it is not clear at the moment that they have a causative role." (PMID 32151005, 2020). "A number of studies suggest a potential role of MACROD2 in cancer; however, it is not clear whether high or low MACROD2 expression levels contribute to tumorigenesis." (PMID 34575904, 2021). "This could suggest that, at least for human cancers, the vast majority of reported SNPs might affect MACROD2 protein function and stability, and not non-coding regulatory regions within its gene." (PMID 30619475, 2018). "Indeed, many of the most commonly deleted CFS-like genes in cancer, including A2BP1, MACROD2, and PDE4D, are not known common fragile sites even in the most recent analyses." (PMID 23805207, 2013).
tumor (10 papers, 2010 to 2022). "Deletions or SNPs in the gene locus of MACROD2 have been often associated with tumor progression, neurological and psychiatric disorders." (PMID 30619475, 2018). "MACROD2 microdeletions may cause chromosomal instability, and the gene could function as a tumor suppressor in CNA-driven tumors." (PMID 36306349, 2022). "Mutations in the APC tumour suppressor are a major driver of sporadic colorectal cancers, where it could be shown that even haploinsufficiency of MACROD2 leads to more and larger adenoma formation." (PMID 32151005, 2020). "Loss of MACROD2 in an APC null background potentially stimulates tumour formation." (PMID 32151005, 2020). "MACROD2 deficiency promoted tumor growth and metastasis and induced EMT in HCC." (PMID 32257385, 2020). "Overall, our results revealed that MACROD2 is frequently affected by SVs in HCC, and its deficiency promotes tumor growth and metastasis by activating GSK-3β/β-catenin signaling." (PMID 32257385, 2020). "Despite the low number of identified mutations in patient tumour samples, several reports have correlated MACROD1 or MACROD2 expression levels with the clinical outcome, as described in the next paragraphs." (PMID 32151005, 2020). "Through in vitro and in vivo experiments, we uncovered the tumor suppressor role of MACROD2 in HCC growth and metastasis." (PMID 32257385, 2020). "Low MACROD2 expression was predictive of tumor recurrence and poor overall survival." (PMID 32257385, 2020). "The down-regulation of MACROD2 was correlated with tumor size (P = 0.021), tumor encapsulation (P = 0.005), vascular invasion (P = 0.020), tumor differentiation (P = 0.044), and tumor node metastasis (TNM) staging (P = 0.011) in the 380 patients with HCC in the FFPE cohort." (PMID 32257385, 2020). "The generalization of these data pointing at MACROD2 as a tumor suppressor is thus unclear." (PMID 30619475, 2018). "It is not clear whether loss or overexpression of MACROD2 contributes to tumourigenesis, or whether both can drive tumour growth dependent on conditions, such as the functionality of the DNA damage repair systems or the oestrogen receptor status." (PMID 32151005, 2020). "Altogether, it appears that loss of MACROD2 as such is not sufficient to drive tumourigenesis, but may have an additive effect in models prone to tumour formation such as loss of APC in colorectal cells." (PMID 32151005, 2020). "Consequently, tumor cells having low protein expression of MACROD2 may effectively enable PARP1-dependent DNA repair." (PMID 30034629, 2018). "Thus, one could speculate that 5-FU treatment combined with a small molecule PARP inhibitor may be lethal for tumor cells that have MACROD2-low protein expression." (PMID 30034629, 2018). "We performed immunohistochemical staining to measure the expression of MACROD2, p-GSK-3β, β-catenin, and the EMT markers E-cadherin, vimentin, and N-cadherin in primary tumor tissues from the 380 patients in the FFPE cohort." (PMID 32257385, 2020). "MACROD2 knockdown in HCC cells markedly enhanced proliferation and invasiveness in vitro and tumor progression in vivo and promoted epithelial–mesenchymal transition (EMT)." (PMID 32257385, 2020). "We validated those findings in samples of tumor tissues from patients with HCC and found that low MACROD2 expression was predictive of poor patient outcomes." (PMID 32257385, 2020). "The difference in the MACROD2 expression level between the tumor and the adjacent normal tissue was greater among the patients with MACROD2 SVs than among those without MACROD2 SVs." (PMID 32257385, 2020). "We found that MACROD2, RBFOX1, and LRP1B were frequently affected by SVs in Chinese patients with HCC, suggesting that SVs in those genes might play a role in tumor development and progression." (PMID 32257385, 2020). "MACROD2 expression levels were lower in the tumor samples than in the paired adjacent non-tumor samples." (PMID 32257385, 2020).
tumor (continued). "Furthermore, human cells transplanted into nude mice displayed increased tumour growth when lacking MACROD2, but a reduced tumour growth when MACROD2 was overexpressed." (PMID 32151005, 2020).
neurological disorders (4 papers, 2019 to 2023). "ADAM23, ANKRD11, and MACROD2 function in the nervous system and are associated with several neurological disorders." (PMID 37805653, 2023). "Macrod2, an ADP-ribose glycohydrolase containing macro domains, plays an important regulatory role in various biological processes, such as tumorigenesis, embryonic development, metabolism balance and various neurological diseases." (PMID 36010655, 2022).
neurodevelopmental disorder (2 papers, 2025). A behavioral and cognitive disorder with onset during the developmental period that involves impaired or aberrant development of intellectual, motor, or social functions. "Mutations or dysregulation of MACROD2 have been associated with several diseases, including neurodevelopmental disorders such as ASD and ID." (PMID 41510264, 2025).
gastrointestinal tumors (1 paper, 2018). "In fact, only in carriers of APC inactivating mutations MACROD2 had epistasis effects enhancing the growth of gastrointestinal tumors." (PMID 30619475, 2018).
MACROD2 also shares sentences with these, for which no sentence is quoted: attention deficit-hyperactivity disorder (3 papers); colorectal tumors (2); pancreas cancer (2); psychiatric disorder (2); antiphospholipid syndrome (1); arrhythmogenic right ventricular cardiomyopathy (1); autoimmune disease (1); bipolar disorder (1); Bradykinesia (1); cerebral infarction (1); cervical cancer (1); chronic kidney disease (1); coronary artery disease (1); Cri-du-chat syndrome (1); diabetic nephropathy (1); eating disorder (1); Insulin resistance (1); lung carcinoma (1); metabolic disorders (1); multiple sclerosis (1); pancreatic cancer (1); prostate carcinoma (1).